FNDC5 (fibronectin type III domain containing 5)
Diseases named in the same sentence as FNDC5 in open-access papers (continued):
Sharing a sentence is not in itself a finding about the gene and the disease.
cerebral infarction (2 papers, 2022 to 2023). An ischemic condition of the brain, producing a persistent focal neurological deficit in the area of distribution of the cerebral arteries. "Li and colleagues reported that circulating irisin concentrations and muscular FNDC5 protein levels reduced after ischemic attack, and its concentrations were negatively correlated to cerebral infarction size and the neurological function deficient scores." (PMID 36267573, 2022). "In this study, we confirmed that FNDC5 promotes the survival of transplanted BMSCs in a rat cerebral infarction model." (PMID 37673870, 2023). "FNDC5 is, therefore, a potential target for therapeutic intervention in treating cerebral infarction." (PMID 37673870, 2023). "However, the molecular pathways by which FNDC5 modulates BMSCs autophagy are undetermined and the protective effect of FNDC5 after BMSC transplantation for treatment of cerebral infarction needs further elucidation." (PMID 37673870, 2023).
gestational diabetes mellitus (2 papers, 2021). "miR-137 restricts the survival and migration of human chorionic trophoblast cells HTR-8/SVneo cells by decreasing fibronectin type III domain containing 5 (FNDC5) in gestational diabetes." (PMID 33817324, 2021). "In gestational diabetes mellitus (GDM), miR-137 reduces the stability and movement of trophoblast cells by suppressing FNDC5 that might contribute to the pathophysiology of placenta cells and the incidence of unfavorable pregnancy complications." (PMID 34956364, 2021).
ischemic stroke (2 papers, 2018 to 2021). A stroke disorder caused by obstruction of blood flow to the brain, due to thrombotic (local blood clot formation) or embolic (due to a blood clot or other material traveling from another site) event. "Based on these observations, both FNDC5 and irisin are likely involved in mediating the neuroprotective effects of exercise against ischemic stroke." (PMID 34108925, 2021).
lymph node metastases (2 papers, 2022 to 2023). "Serum Ir levels did not correlate with FNDC5/Ir expression in BC tissues but were associated with lymph node metastasis (N) and histological grade (G)." (PMID 37239973, 2023). "As in the case of irisin levels assessed by IHC, we observed higher FNDC5 gene expression in patients without lymph node metastases (mean 9.092 ± SD 1.7; p = 0.0395) compared to subjects with metastases (mean 3.679 ± SD 0.9)." (PMID 35408891, 2022).
multiple myeloma (2 papers, 2017 to 2022). "For example, FNDC3A can bind FAM46C to inhibit multiple myeloma progression by regulating autophagy, and FNDC5 regulates the conversion of white fat to brown fat and improves insulin resistance by regulating the macrophage polarization, thereby reducing the validation response of adipose tissue." (PMID 36056336, 2022).
non-small cell lung carcinoma (2 papers, 2019 to 2021). A group of at least three distinct histological types of lung cancer, including non-small cell squamous cell carcinoma, adenocarcinoma, and large cell carcinoma. "In addition, the FNDC5 gene expression was found in human non-small cell lung cancer (NSCLC, adenocarcinoma AC and squamous cell carcinoma SCC) tissues and stromal fibroblasts." (PMID 34071869, 2021).
osteoarthritis (2 papers, 2021 to 2024). A noninflammatory degenerative joint disease occurring chiefly in older persons, characterized by degeneration of the articular cartilage, hypertrophy of bone at the margins and changes in the synovial membrane. "Primary mouse chondrocytes isolated from mice with destabilized medial meniscus (DMM)-induced osteoarthritis had significantly reduced FNDC5 and LC3 expression and weak immunoreactivity of the proliferating cell nuclear antigen (PCNA)." (PMID 34502045, 2021).
pancreatitis (2 papers, 2024 to 2025). Inflammation of the pancreas. "Together, these results indicate that pancreatitis induction up-regulates the expression and secretion of PL suggestively via the activation of the PPARγ-PGC1α-FNDC5 pathway." (PMID 38927047, 2024). "Together, these results indicate the involvement of the PPARγ-PGC1α-FNDC5 in cellular stress conditions such as pancreatitis and the ER stress state." (PMID 38927047, 2024). "Pancreatitis induction (cerulein (cer)) resulted in a significant up-regulation of the PPARγ-PGC1α-FNDC5 axis, PL expression and secretion and endoplasmic reticulum (ER) stress unfolded protein response (UPR) signal-transduction markers (CHOP, XBP-1 and ATF6)." (PMID 38927047, 2024). "Next, we aimed to explore whether pancreatitis induction affects the PPARγ-PGC1α-FNDC5 axis and PL expression and secretion." (PMID 38927047, 2024). "Cer-pancreatitis activated the PPARγ-PGC1α-FNDC5 pathway and triggered the activation of the UPR." (PMID 38927047, 2024). "Irisin addition in the cer-pancreatitis state resulted in a significant down-regulation of the PPARγ-PGC1α-FNDC5 axis, PPARγ nucleus-translocation and inflammatory state (TNFα and IL-6) in parallel to diminished PL expression and secretion (in vitro and ex vivo models)." (PMID 38927047, 2024).
prediabetes (2 papers, 2017 to 2022). "A related study reported that, after 12 weeks of exercise, the levels of PGC-1α and FNDC5 (fibronectin type III domain containing 5) in prediabetes patients and healthy controls slightly increased." (PMID 35886989, 2022). "Taken together, this evidence points to a potential compensatory role of FNDC5/irisin as a myo‐adipokine, opposing excess body weight and the development of insulin resistance in the stages of prediabetes." (PMID 28676551, 2017).
renal carcinoma (2 papers, 2018 to 2022). A carcinoma arising from the epithelium of the renal parenchyma or the renal pelvis. "FNDC5/Irisin may be used as a diagnostic biomarker for renal cancer." (PMID 29522296, 2018). "In our research renal cancer patients FNDC5/irisin and CEA levels were significantly higher compared with the control group." (PMID 29522296, 2018). "The best cut-off points for FNDC5/irisin were >105pg/mL and CEA were >2.67ng/mL for renal cancer." (PMID 29522296, 2018).
rhabdomyosarcoma (2 papers, 2014). A rare aggressive malignant mesenchymal neoplasm arising from skeletal muscle. "Strong connection links on certain genes (TNNT1 and FNDC5 in rhabdomyosarcoma (RMS); FCGRT and OLFM1 in Ewing’s sarcoma (EWS)) suggested their potency as central hubs in the interconnection of genes with different functionalities." (PMID 25025207, 2014). "A significant increase of PPARGC1A and FNDC5 mRNA abundance was noticed in cultured human rhabdomyosarcoma cells after treatment with a combination of omega-3 fatty acids for 24 or 48 hours." (PMID 24498244, 2014).
scleroderma (2 papers, 2023 to 2025). Scleroderma is a rare autoimmune connective tissue disorder characterized by abnormal hardening of the skin and, sometimes, other organs. "They identified NTN1, VEGFD, MMP2, FGF2, and FNDC5 as potential players in how the ADSCs secretome may disrupt vascular and perivascular inflammation hubs in scleroderma and thereby promote angiogenesis and lymphangiogenesis." (PMID 40584563, 2025). "ADSCs also expressed fibronectin type III domain-containing protein 5 (FNDC5), which interacted with ITGB5 and additionally with ITGAV in scleroderma on various subclusters." (PMID 37443817, 2023). "ADSCs also expressed FNDC5, a fibronectin, which interacted with ITGB5 and additionally with ITGAV in scleroderma." (PMID 37443817, 2023). "The few effector molecules that were identified, including NTN1, VEGFD, MMP2, FGF2, and FNDC5, provide evidence for the anti-fibrotic and anti-inflammatory effects of the ADSC secretome; however, these few factors cannot explain all observed effects on scleroderma skin after autologous fat grafting." (PMID 37443817, 2023).
type 1 diabetes (2 papers, 2021 to 2024). "In streptozotocin (STZ)-induced type 1 diabetic mice, high-fat diet (HFD)-induced obese mice and db/db mice, the circulating irisin as well as FNDC5 gene expression in subcutaneous fat was downregulated." (PMID 33672565, 2021).
vitamin D deficiency (2 papers, 2023 to 2024). A nutritional condition produced by a deficiency of VITAMIN D in the diet, insufficient production of vitamin D in the skin, inadequate absorption of vitamin D from the diet, or abnormal conversion of vitamin D to its bioactive metabolites. "Patients with CKD have several risk factors that dysregulate the PGC-1α–FNDC5 axis, such as vitamin D deficiency and the accumulation of protein-bound uremic toxins." (PMID 36817773, 2023). "Studies on rats with vitamin D deficiency have shown decreased irisin levels, while VDS alters FNDC5 gene expression in diabetic rat models." (PMID 39064638, 2024).
amyloid (1 paper, 2025). "Synaptic plasticity and memory in amyloid pathology mimicking AD mouse models can be rescued by boosting brain levels of FNDC5/irisin, and peripheral overexpression of FNDC5/irisin rescues memory impairment." (PMID 40274715, 2025).
chronic heart failure (1 paper, 2020). "Since FNDC5 expression is significantly decreased in ischemic cardiomyopathy, in severe chronic heart failure mice, application of irisin may be beneficial as a novel therapeutic approach for treatment of heart disease." (PMID 32257109, 2020).
colitis (1 paper, 2022). Inflammation of the colon. "Moreover, FNDC4 reportedly plays a role in promoting fat browning, similar to FNDC5, and is an anti-inflammatory factor capable of improving colitis symptoms by specifically binding to macrophages." (PMID 36056336, 2022).
colon cancer (1 paper, 2025). "In vitro experiment results demonstrated a strong association between FNDC5 expression levels and the proliferative, migratory, and invasive abilities of colon cancer cells." (PMID 40313961, 2025).
Crohn disease (1 paper, 2016). A gastrointestinal disorder characterized by chronic inflammation involving all layers of the intestinal wall, noncaseating granulomas affecting the intestinal wall and regional lymph nodes, and transmural fibrosis. "Intestinal biopsies obtained during ileocolonoscopy from 52 IBD patients (21 with Crohn's disease, 29 with ulcerative colitis and 2 with unclassified IBD) and 19 controls were analysed for FNDC4 and FNDC5 expression using quantitative reverse transcription–PCR (RT–qPCR)." (PMID 27066907, 2016).
diffuse type adenocarcinoma (1 paper, 2022). An adenocarcinoma characterized by the presence of a diffuse cellular infiltrate which is composed of poorly cohesive cells with minimal or no glandular formations. "Based on TCGA dataset, we found that the expression of FNDC5 was decreased in intestinal-type adenocarcinoma compared with diffuse-type adenocarcinoma." (PMID 36386179, 2022).
dyslipidaemia (1 paper, 2024). "The association found in men is supported by experiments in which Fndc5 was transgenically overexpressed in male ApoE−/− mice, a model used to investigate atherogenic dyslipidaemia." (PMID 39040132, 2024).
Genetic obesity (1 paper, 2013). "Rats with either diet-induced obesity (DIO) or genetic obesity (Zucker rats) showed a significant increase of FNDC5/irisin secretion in both SAT and VAT tissues compared with their lean counterparts." (PMID 23593248, 2013).
Hypercholesterolemia (1 paper, 2024). An increased concentration of cholesterol in the blood. "In the treatment of hypercholesterolemia, the use of statins (e.g., simvastatin) increases FNDC5 mRNA expression and IR secretion both in vitro and in vivo, highlighting the potential cholesterol-lowering effects of IR." (PMID 39458475, 2024).
hypoparathyroidism (1 paper, 2024). Hypoparathyroidism is an endocrine disorder in which the parathyroid glands in the neck do not produce enough parathyroid hormone (PTH). "Our results show a decreased expression level of FNDC5, the gene coding for irisin induced by the altered extracellular ions condition, strongly suggesting that alteration of this hormone level might further contribute to the muscle damage observed in patients affected by hypoparathyroidism." (PMID 37819413, 2024).
inflammatory bowel disease (1 paper, 2025). A spectrum of small and large bowel inflammatory diseases of unknown etiology. "In addition, previous study has shown that FNDC4 and FNDC1, but not FNDC5, are significantly increased in human inflammatory bowel disease, and FNDC4 has been described as an anti-inflammatory factor." (PMID 39567831, 2025).
injury (1 paper, 2025). Damage inflicted on the body as the direct or indirect result of an external force, with or without disruption of structural continuity. "In neuron-specific Sirt3 knockout mice, FNDC5 fails to rescue TBI-induced mitochondrial damage and brain injuries, suggesting FNDC5/irisin plays a protective role against acute brain injury by promoting SIRT3-dependent mitochondrial biogenesis." (PMID 41373506, 2025).
ischemic cardiomyopathy (1 paper, 2024). Ischemic cardiomyopathy is a cardiomyopathy in which a weakness in the muscle of the heart due to inadequate oxygen delivery to the myocardium with coronary artery disease being the most common cause. "Indeed, in animal studies, reduced skeletal muscle FNDC5 expression in ischemic cardiomyopathy was likely modulated by inflammatory cytokines and/or angiotensin-II via the down-regulated PGC-1α, which corresponded to low irisin production." (PMID 39200291, 2024).
ischemic heart disease (1 paper, 2020). "In addition, FNDC5/irisin is responsible for the repair of cardiac tissue after an ischemic heart disease episode as it induces cell proliferation through activation of cardiac progenitor cells." (PMID 32257109, 2020).
liver diseases (1 paper, 2023). "FNDC5/irisin is involved in different types of liver diseases, such as NAFLD, multiple detrimental insults-induced liver injury, and hepatic malignancy." (PMID 36835571, 2023).
lung adenocarcinoma (1 paper, 2022). A carcinoma that arises from the lung and is characterized by the presence of malignant glandular epithelial cells. "Conversely, upregulated FNDC1, FNDC4, FNDC5, and FNDC6 were associated with worse survival in patients with lung adenocarcinoma." (PMID 36626432, 2022).
lung squamous cell carcinoma (1 paper, 2022). "The highest increase in FNDC5 gene expression in IMR-90 cells was observed when NCI-H1703 cells, which are equivalent to lung squamous cell carcinoma, were added to the insert." (PMID 36430689, 2022).
mood disorder (1 paper, 2023). A cognitive disorder a disturbance in which the person's mood is hypothesized to be the main underlying feature. "Thus, it could be hypothesized that the activation of the FNDC5/irisin pathway in the brain regions mainly involved in mood disorders could contribute to the antidepressant and anxiolytic-like effects of irisin." (PMID 37047687, 2023).
muscle disorders (1 paper, 2022). "In the elderly, it seems the use of irisin to target AMPK-PGC1α-FNDC5 and IGF-1/Akt/mTOR pathways appears to prevent muscle disorders." (PMID 35250869, 2022).
myositis (1 paper, 2023). "Therefore, the reduced expression of the transmembrane protein FNDC5 in muscle fibers of these patients suggests the possible implication of its deficiency in muscle atrophy caused by myositis." (PMID 36768791, 2023).
neuroblastoma (1 paper, 2017). Neuroblastoma (NB) is the most common solid, extracranial childhood tumor. "In addition, overexpression of either PGC-1α or FNDC5 reversed the suppressive effects of the Aβ1−42 oligomers on the expression of BDNF in neuroblastoma 2a (n2a) cells." (PMID 28377712, 2017).
ovarian carcinoma (1 paper, 2021). A malignant neoplasm originating from the surface ovarian epithelium. "Protein expression of FNDC5/irisin was higher in breast and ovarian cancer tissue specimens, as well as in oncocytic papillary thyroid carcinoma and in a series of gastrointestinal cancers compared to nonneoplastic tissues." (PMID 33688343, 2021).
ovarian serous adenocarcinoma (1 paper, 2022). An adenocarcinoma that arises from the ovary and is characterized by the presence of malignant epithelial cells that, in well differentiated tumors, resemble the epithelium of the fallopian tube or, in poorly differentiated tumors, show anaplastic features and marked nuclear atypia. "Meanwhile, the expression levels of FNDC4 and FNDC5 were lower in ovarian serous adenocarcinoma in the Yoshihara dataset." (PMID 36626432, 2022).
pancreatic cancer (1 paper, 2022). "In pancreatic cancer, FNDC5 inhibited the growth of pancreatic cancer cells through the AMPK-mTOR pathway, and inhibited the migration and invasion of pancreatic cancer cells through the inhibition of EMT." (PMID 36386179, 2022).
pituitary adenomas (1 paper, 2023). "The expression levels of ANXA2, PMAIP1, SPRY2, C2CD4A, APOD, FGF14 and FKBP10 were significantly upregulated while FNDC5 and MAP3K4 were downregulated in the invasive gonadotrophic pituitary adenomas compared to the non-invasive ones." (PMID 36750863, 2023).
preeclampsia (1 paper, 2021). Preeclampsia is a hypertensive disorder of pregnancy that is characterized by new-onset hypertension with proteinuria presenting after 20 weeks of gestation, and depending on mild or severe forms may initially present with severe headache, visual disturbances, and hyperreflexia. "In patients with preeclampsia, irisin expression has a negative correlation with blood pressure, but FNDC5 expression in the placenta has a positive correlation with blood pressure." (PMID 34440871, 2021).
prostate tumors (1 paper, 2022). "In the Oncomine database, there are only 3 datasets for FNDC3A, FNDC4, and FNDC5, which indicate statistically notable distinctions between prostate tumors and normal tissues." (PMID 36626432, 2022).
renal osteodystrophy (1 paper, 2025). Abnormalities of bone mineral metabolism associated with chronic kidney disease. "Mechanistically, we have elucidated the PGC-1α/FNDC5/irisin axis in skeletal muscle and the direct proosteogenic role of irisin-integrin αvβ5 signaling on osteoblasts in renal osteodystrophy." (PMID 39883525, 2025).